EZH2 (enhancer of zeste 2 polycomb repressive complex 2 subunit)
Diseases named in the same sentence as EZH2 in open-access papers (continued):
Sharing a sentence is not in itself a finding about the gene and the disease.
tumor (continued). "In summary, EZH2 inhibitors upregulate the infiltration of immune cells in the tumor microenvironment and induce reprogramming of immunosuppressive cells, which enhances the antitumor efficacy of PARP inhibitors." (PMID 36263120, 2022). "Although the oncogenic role of EZH2 has been documented, some in vivo experiments suggest a tumor-suppressive function of EZH2." (PMID 35269532, 2022). "According to TCGA-BRCA data, the expression of the positive genes of risk score (HJURP, IFI27, RAD51AP1, EZH2, DNMT3B, SLC7A5, DBF4 and USP18) in tumors was higher than that in normal and tumor-adjacent tissues." (PMID 36341435, 2022). "It has been shown to act as a tumour inducer in GC, in part through EphB3 inhibition through direct interaction with EZH2 and LSD1." (PMID 35327654, 2022). "Epigenetic silencing of tumor suppressor gene expression via H3K27me3 modification has been viewed as a common mechanism accounting for EZH2 oncogenic functions." (PMID 35013218, 2022). "Our data suggest a potential tumor suppressive role for EZH2 in DMG that suggests careful investigation of the use of EZH2 inhibitors in the clinic." (PMID 35395831, 2022). "EZH2 depletion suppresses the growth and invasion of BC cells while EZH2 inhibitors alone exert little anti-tumor effect." (PMID 36038549, 2022). "It is expected that the inhibition or over-expression of EZH2 in each tumor type would influence different processes due to a multitude of cell-specific transcriptional targets." (PMID 36230683, 2022). "As efforts move forward to modulate EZH2 for anti-tumor benefit with small molecule inhibitors, there will need to be human-centric studies on the role of EZH2 in human TILs." (PMID 36684449, 2022). "These interesting issues suggest that epigenetic regulators (like LSD1 or EZH2) regulate tumor cell growth in vitro through both dsRNA-IFN stimulation and possibly an intrinsic proliferation program." (PMID 35912007, 2022). "EZH2 is one of the key factors in the response of tumor cells to DNA damage and determines their subsequent cell fate." (PMID 36263120, 2022). "Immunohistological (IHC) staining of EZH2 in sections of RKO/Par4a-derived tumor tissues compared with tissues of small tumors derived by parental RKO cells resulted in the following outcome." (PMID 35955891, 2022). "EZH2 can also drive tumor cells to release certain mediators to affect the transport and activity of immune cells." (PMID 36713412, 2022). "This miRNA cluster negatively regulates EZH2 expression to elevate M1 polarization of macrophages and to enhance anti-tumor immunity." (PMID 35236381, 2022). "These RBPs were differently expressed in ccRCC tumor samples compared with adjacent normal kidney tissues (all p < 0.001), except for EZH2 (p = 0.962)." (PMID 34420511, 2022). "With the in-depth study of EZH2, it will help us to better understand the function of EZH2 and provide new ideas for targeting EZH2 in tumor therapy." (PMID 36313363, 2022). "EZH2 can also interact with other tumor-promoting factors such as YY1 to down-regulate miRNA expression." (PMID 35236381, 2022). "Our results showed that the expression of EZH2 mRNA in HCC primary tumor tissue (n = 371) was significantly higher than that in liver tissue adjacent to the tumor (n = 50)." (PMID 36071871, 2022). "In this study, we found that EZH2 rs6950683 and rs3757441 SNPs (TC + CC genotype) are related to the tumor size of TNBC patients under 60 years old." (PMID 35813302, 2022). "High EZH2 and low DAB2IP expression was associated with poor outcomes, including pathologic stage, tumor size, metastatic status and Fuhrman grade." (PMID 35562342, 2022). "It is noteworthy that most of studies have focused on revealing the role of tumor-promoting lncRNAs in cancer progression via EZH2 regulation." (PMID 35236381, 2022). "EZH2 is a highly expressed protein in tumor tissues and promotes tumor formation by downregulating E-cadherin." (PMID 36518886, 2022).
tumor (continued). "The previous clinical trial was in phase I and highlighted that low half-life survival of EZH2 inhibitors limits their tumor-suppressor activity." (PMID 35236381, 2022). "In the current study, we aim to investigate how EZH2 modulates the polarization of macrophages in the tumor microenvironment (TME) of CRC, and compare the role of two different EZH2 inhibitors, EPZ6438 and GSK126." (PMID 35432300, 2022). "EZH2 activates or inhibits the expression of downstream genes in a PRC2-dependent/-independent manner in different types of tumor cells, and it is involved in a variety of biological processes, including cell proliferation and apoptosis." (PMID 36000567, 2022). "The study found a significantly higher level of EZH2-positive cells in the SF8628 control tumor than in the PBT24 control." (PMID 35216113, 2022). "In the EZH2 knockdown group, tumor cell MHC class expression levels were increased compared with the control group." (PMID 35912007, 2022). "Existing literature indicates that the role of EZH2 in tumor growth and progression is highly context-dependent and to some extent, it exerts an opposite effect in different types of cancers." (PMID 36446780, 2022). "As expected, administration of DZNep depleted MYCN (and Ezh2) concomitantly with a dramatic inhibition of primary tumor cell growth in vitro, whereas the enzymatic inhibitor GSK126 exhibited minimal effects." (PMID 35013218, 2022). "Loss of SMARCB1 impairs SWI/SNF’s function, leading to deregulated PRC2 activity, particularly of the catalytic subunit, EZH2, which is driving tumor progression." (PMID 35159116, 2022). "Meanwhile, downregulation of Zeste Homolog 2 (EZH2) can reduce the methylation level of RUNX3, and silencing EZH2 can inhibit the re-methylation of tumor cells." (PMID 36476345, 2022). "In sum, downstream of EWSR1-FLI1, EZH2 prevents EwS cell differentiation and maintains a stem cell-like state, resulting in oncogenic transformation and tumor progression." (PMID 35740349, 2022). "The difference between tumor and normal was also more significant for EZH2 specifically bound genes in HepG2 cells than others (p-value = 0, t-test)." (PMID 36578923, 2022). "EZH2 overexpressed tumors often exhibit immunosuppressive tumor microenvironment and immunotherapy resistance." (PMID 36532284, 2022). "Similar to SNHG16, SNHG6 regulates gene expression transcriptionally by recruiting EZH2 to promoter regions of different tumor suppressor genes, such as P27 and P21, and represses their expression through methylation of their promoters." (PMID 35740344, 2022). "In this study, we aimed to investigate the regulation of EZH2 on macrophage polarization in the tumor microenvironment by applying both a co-culturing system and tumor-bearing mouse model." (PMID 35432300, 2022). "The generally accepted view is that EZH2 functions as an oncogenic factor in a majority of solid cancers, while it acts as a tumor suppressor in some blood malignancies (e.g., T cell acute lymphoblastic leukemia)." (PMID 36230683, 2022). "In the process of CRC, LINC00114 expression trends to up-regulate, and down-regulating LINC00114 inhibits proliferation in vitro, and retards tumor formation in vivo via reducing EZH2/DNA methyltransferase 1-induced methylation of miR-133b promoter." (PMID 35414117, 2022). "FOXO1 is a tumor repressor that is believed to be down-regulated in cancer through negative regulation by the enhancer of zeste homolog 2 (EZH2)." (PMID 35577773, 2022). "These examples show that EZH2 hyperactivity promotes SCLC tumor formation by affecting both the immunogenicity and plasticity of transforming cells." (PMID 36509828, 2022). "Tazemetostat, an EZH2 inhibitor, is currently under evaluation in different Phase I and II clinical trials in tumours with SMARCB1, SMARCA4 and EZH2 mutations with positive results in patients with different solid tumours." (PMID 36138075, 2022).
tumor (continued). "In summary, our observations using Ezh2 loss- and gain-of-function DMG mouse models suggest a ‘tumor suppressor’ role of EZH2 in DMG." (PMID 35395831, 2022). "A higher density of CD163+ TAMs was found in tumor tissues with stronger EZH2 staining, showing a significant positive correlation." (PMID 36038549, 2022). "These contradictory effects of EZH2 on lung metastasis versus bone metastasis suggest that EZH2 inhibitors’ effects are depended on the tumor microenvironment." (PMID 35538070, 2022). "Overall, EZH2 has proven to be a driving force for immunoediting and resistance to tumor immunotherapy, primarily due to its epigenetic reprogramming of T-cell antigen-presenting genes." (PMID 35911718, 2022). "Specifically, in DMG where 80% of cases express the mutant H3K27M histone, focal gains of the H3K27me3 mark on critical tumor suppressors such as Cdkn2a among others have been implied as an indirect consequence of residual EZH2 activity." (PMID 35395831, 2022). "Next, we categorised the tumours (n = 173) into three EZH2/p65 expression groups: low (with low p65 and EZH2 expression; n=70), intermediate (with high levels of either p65 or EZH2; n = 72), and high-(with high levels of either p65 or EZH2;n = 31)." (PMID 36263173, 2022). "The nomogram showed that a larger tumor size and higher EZH2, GRPEL2, and NDRG1expression predicted the higher likelihood of a worse prognosis." (PMID 36686830, 2022). "Concordantly, treatment with EZH2 inhibitors reverses this signature and decreases tumor growth in-vitro and in-vivo." (PMID 36589742, 2022). "Mechanistically, this anti-tumor activity is mediated via recruiting EZH2, suggesting its role in tumor suppression." (PMID 35236381, 2022). "In a variety of malignant tumor models, EZH2 mediates H3K27me3 and plays a key role in driving tumor growth and metastasis." (PMID 36316365, 2022). "Of note, both tumor-suppressive and tumor-promoting functions of EZH2 have been reported in cancer development." (PMID 36555314, 2022). "The importance of PRC2 in MYCN-induced tumor formation is shown by the suppression of tumor development in response to EZH2 inhibition." (PMID 35681734, 2022). "Although a few studies have examined tumor-suppressor lncRNAs, more experiments are needed to reveal lncRNA and EZH2 interaction in cancer." (PMID 35236381, 2022). "In this sense, genotyping of ctDNA by CAPP-Seq allows the recovery of 100% of the tumor-confirmed actionable mutations of DLBCL, such as EZH2, MYD88, and CD79B." (PMID 36230571, 2022). "Our results were in line with previous studies, in which the EZH2 positivity rate increased with the increasing WHO tumour grades." (PMID 36292072, 2022). "Lastly, cell proliferation and migration, in addition to tumor xenograft tests, were used to validate the biological significance of the circSYPL1/miR-506-3p/EZH2 signaling axis through overexpression or otherwise silencing." (PMID 35345511, 2022). "These two studies indicate that caution is needed when deducing general conclusions on the roles of EZH2 in the cisplatin resistance of each tumor type." (PMID 36230683, 2022). "Further rescue experiments indicated that EZH2 knockdown mimicked the tumor inhibitory effects of miR-506-3p in cell models, while EZH2 overexpression obviously rescued the inhibitory effects of miR-506-3p." (PMID 35154460, 2022). "There appears increasing evidence that EZH2 can not only inhibit tumor genes but also play roles in manipulating collective immune homeostasis as well as immune-related cells, especially in the development, differentiation, and function of T cells." (PMID 36195655, 2022). "GEPIA and TIMER were adopted to detect the possible relationship of EZH2 expression with tumour-infiltrating immune cells (TIICs)." (PMID 35659256, 2022). "Similar changes in TME are also observed in tumor tissues treated with other agents, such as inhibitors of KMT6A (EZH2), KDM1A (LSD1), PRMT5, and BET proteins." (PMID 35935878, 2022).
tumor (continued). "Margueron and Reinberg demonstrated that EZH2 was capable of silencing a bundle of tumor suppressor genes via methylation of lysine 27 of histone 3 (H3K27) of target genes." (PMID 35419058, 2022). "In 7 randomly selected GBM samples and paired normal tissues, EZH2-92aa was expressed at high levels in the tumour tissues." (PMID 35970825, 2022). "29out of the 36 patients with low expression of EZH2 achieved good tumor regression, whereas only 5 of the 44 patients with high expression of EZH2 achieved good tumor regression (P < 0.001)." (PMID 35280723, 2022). "EZH2 is prone to mutations in diffuse large B-cell lymphoma, which leads to acquired major histocompatibility complex (MHC)-II defects and tumor immune escape." (PMID 36552722, 2022). "Studies have shown that tumor cell-mediated EZH2 exerts its epigenetic catalytic subunit methyltransferase ability, resulting in epigenetic changes in the TME into an immunosuppressive network." (PMID 35911718, 2022). "Epigenetic silencing of tumor suppressor gene expression via H3K27me3 modification has been viewed as a predominant mechanism accounting for EZH2 oncogenic functions." (PMID 35013218, 2022). "On one hand, enhancer of zeste homologue 2 (EZH2) and lysine 27 on histone H3 (H3K27) methyltransferase (H3K27me) highly mutate in GBM tumor cells, and lead to a poor outcome of GBM." (PMID 35572545, 2022). "EZH2 can induce tumorigenesis by affecting tumor-suppressive genes and initiating cancer-related molecular processes like miRNA silencing, non-canonical transcription regulation, and NF-kB activation." (PMID 35656182, 2022). "We will explore the detailed mechanisms of EZH2 regulation regarding the tumor immune microenvironment in vitro and in vivo systematically in the near future." (PMID 36358967, 2022). "Existing studies have recognized the critical roles played by EZH2 in tumor angiogenesis and cell proliferation, as well as cell differentiation and apoptosis." (PMID 35627262, 2022). "Constitutive active KRAS signaling, for instance, switches tumor-suppressive EZH2 functions evident in early pancreatic carcinogenesis into tumor-progressive activities in advanced neoplasia." (PMID 35884510, 2022). "Together, these data indicate that activated ACK1/EZH2 epigenetic signalling in tumour cells depletes the tumour microenvironment of the T-cell attractant CXCL10, maintaining T cells in an inactive state." (PMID 36376335, 2022). "Although previous experiments demonstrate the anti-tumor activity of EZH2 in cancers via reducing expression levels of downstream targets, it appears that its down regulation by lncRNAs can reduce cancer progression." (PMID 35236381, 2022). "EZH2 can manipulate the metabolic activity of tumor cells through epigenetic regulation, which in turn affects tumor progression." (PMID 36195655, 2022). "Pharmacological inhibition of EZH2 augmented neural progenitor cell proliferation, supporting the tumor suppressive role of EZH2." (PMID 35395831, 2022). "We further detected the expression of EZH2 in tumour tissues from 94 Chinese ESCC patients as well as 61 adjacent normal tissues by immunohistochemistry." (PMID 35604910, 2022). "This provided further evidence that G9A/EZH2 blockade drives an antitumoral response, not only directly in the tumor deposits but also more systemically." (PMID 35131874, 2022). "Compared with the scramble group, the EZH2 knockdown group tumor growth was significantly inhibited." (PMID 35912007, 2022). "Recently, a computer-aided structure-based drug design method has been able to develop small molecule inhibitor of HOTAIR (e.g., AC1NOD4Q) which particularly interferes with the HOTAIR/EZH2 interaction and prevents tumor metastasis in breast cancer models." (PMID 35755302, 2022).
tumor (continued). "Mice were treated with EZH2 inhibitors combined with CL or PBS to observe how the combined application of macrophage depletion affected the anti-tumor function of EZH2 inhibitors." (PMID 35432300, 2022). "In this review paper, we explore the work that analyzed the joint action of EZH2 inhibitors and cisplatin in different tumor types." (PMID 36230683, 2022). "Out of the 36 patients with low expression of EZH2, 30 presented with tumor decline, whereas 8 of the 44 patients with high expression of EZH2 presented with tumor decline (P < 0.001)." (PMID 35280723, 2022). "Subsequently, the relationships between EZH2 expression and tumor-related immune cell infiltration, immune checkpoint blockade, and the immunotherapy response were explored in HCC." (PMID 35627262, 2022). "Chi-squared analysis demonstrated that EZH2 protein expression was significantly correlated with tumor location (P = 0.005)." (PMID 36401232, 2022). "High levels of EZH2 often correlate with tumor stage and poor prognosis, while genetic deletion of EZH2 can block proliferation and survival in tumor cell lines and mouse models." (PMID 35013218, 2022). "Independent experiments showed that tumor cells of both entities are sensitive to inhibition of EZH2 and EED in vitro." (PMID 34762160, 2022). "In this work we demonstrated that a subset of PanNENs expressed EZH2 and that its expression highly correlated with higher tumor grade and disease stage." (PMID 34638497, 2021). "In conclusion, our study provided evidence for the first time that PWAR6 exerts tumour suppressor activity in human PDAC cells by interacting with EZH2 and facilitating its repression of YAP1, thus mediating proliferation, apoptosis and metastasis of PDAC." (PMID 33834618, 2021). "We showed that inhibition of EZH2 in vitro and in vivo in PanNEC and PanNET models reduced growth, cell survival, and tumor burden." (PMID 34638497, 2021). "EZH2 is overexpressed in PCs, contributing to tumor initiation and progression, and negatively regulating interferon-stimulated genes, including Th1-type chemokines, immune checkpoint molecules, and the major histocompatibility complex (MHC)." (PMID 34830196, 2021). "HOXA11-AS is thought to bind directly to LSD1, EZH2, WDR5, STAU1, DNMT1 and AGO2 in tumor cells, acting as a frame for EZH2 and LSD1/DNMT1 to downregulate PRSS8, KLF2 and P21 expression, thus promoting GC." (PMID 35155211, 2021). "An increasing number of reports have demonstrated that a variety of EZH2 target genes are tumour suppressors, such as HOXA7, HOXA9, DAB2IP, P16 and P21." (PMID 34775498, 2021). "Although TCGA tumors were not pathologically reviewed for TIL characteristics, we were able to incorporate a cytolytic activity score and a transcriptome-based tumor-immune phenotype to evaluate EZH2 in context of the immune features." (PMID 34140011, 2021). "In another study, genetic depletion of EZH2 in Treg cells led to robust anti-tumor immunity in mouse models." (PMID 34930302, 2021). "Of note, the staining pattern of EZH2 was very homogeneous, with most cases displaying intermediate to strong staining most of the tumor cells." (PMID 34945856, 2021). "The 5 mM MgDCA impact was more potent and had similar effects on U87 MG and PBT24 tumors, and its impact was also reflected in changes in PCNA and EZH2 expression in tumor cells." (PMID 33716589, 2021). "As expected, the knockdown of EZH2 by siRNA dramatically inhibited cell proliferation; meanwhile, the overexpression of EZH2 significantly promoted the growth of tumor cells." (PMID 34381816, 2021). "The variants included age at diagnosis, Federation International of Gynecology and Obstetrics (FIGO) stage, histological subtype, tumor categories, EZH2 expression and pCHK1 expression." (PMID 33408782, 2021). "Second, the effect of inhibiting EZH2 and G9a on in vitro transformation and in vivo tumor development was evaluated using EPZ6438 and UNC0642, DZNep, and omega-3 fatty acids." (PMID 33632299, 2021).